MALAT1 (metastasis associated lung adenocarcinoma transcript 1)
Diseases named in the same sentence as MALAT1 in open-access papers (continued):
Sharing a sentence is not in itself a finding about the gene and the disease.
tumor (continued). "MALAT1 is abnormally overexpressed in NSCLC tumor cells and tissues." (PMID 36419933, 2022). "Moreover, MALAT1 expression was significantly higher in advanced stages III–IV of tumor-node-metastasis (TNM) than in early stages I–II of CRC." (PMID 35922756, 2022). "Further work is needed to clarify how MALAT1 functions in the tumor microenvironment." (PMID 36685103, 2022). "Silencing of miR-378a-3p targets, MALAT1 and NEAT1, significantly impairs tumorigenic properties of CRC-SCs, supporting the critical role of miR-378a-3p in CRC carcinogenesis as a tumor-suppressor factor by establishing a finely tuned crosstalk with lncRNAs MALAT1 and NEAT1." (PMID 35814429, 2022). "It suggested that the mechanism of lncRNA MALAT1 in the growth and invasion of different tumor cells is different, which may be related to the microenvironment and physiological barriers of different tumors." (PMID 35706002, 2022). "The nanocomplex delivery of MALAT1 targeting siRNA in glioblastoma patients increased the sensitivity of the tumor to temozolomide (TMZ) treatment, while a novel ASO drug against non-coding mitochondrial RNA demonstrated good tolerance in a phase one clinical study." (PMID 36077530, 2022). "A current study by He-S and colleagues highlighted the fact that EWS-FLI1 induced tenascin-C (TNC) may regulate ES tumor progression through targeting the lncRNA MALAT1, and that this may be done by integrin α5β1-mdiated YAP activation." (PMID 35455947, 2022). "Moreover, SOX17 reduced the irradiation tolerance of ESCC cells by reducing HIF1α expression via the MALAT1-miR-199a axis, and attenuated tumor formation in nude mice." (PMID 35614065, 2022). "Differential expression analysis revealed significant divergence in lncRNA profile between parental tumors and tumor-derived cell cultures in vitro, including the following particles: MALAT1, CASC2, H19, TUSC7, XIST, RP11-838N2.4, DLX6-AS1, GLIDR, MIR210HG, SOX2-OT." (PMID 33245508, 2022). "Recent studies have reported that MALAT1 exhibits both oncogenic and tumor suppressive functions." (PMID 35558512, 2022). "Moreover, lncRNA Malat1 has been targeted using ASOs in several cancer types preclinically to reduce tumor growth in vitro and in vivo." (PMID 36009578, 2022). "Moreover, the expression of MALAT1 was found to be positively associated with the mRNA levels of INTU and IFT88 in LUAD and UCEC tumor samples." (PMID 36084949, 2022). "Moreover, despite the fact that MALAT1 is considered as a broad-spectrum tumor-promoting transcript, the functional module consisting of MALAT1, PTBP1, and PSF appears to have greater clinical value in HCC." (PMID 36563164, 2022). "Moreover, a prior study further highlighted the correlation between MALAT1 and tumor-node-metastasis stage, distant metastasis, and survival outcomes of patients, which is also in line with our findings." (PMID 35813865, 2022). "Generally, MALAT1 high RNA level in multiple tumor tissues is related to poor patient prognosis." (PMID 34308750, 2021). "The higher expression of AGT in COAD suggested that MALAT1 might promote tumor development through AGT." (PMID 34671200, 2021). "Thus, MALAT1 acted as a tumor promoter at least in part by binding miR-217 and sequestering the molecule in the nucleus, thereby promoting oncogenic KRAS expression in PC." (PMID 34760707, 2021). "However, different or opposite results also were raised in some studies: tumor suppressive function of MALAT1." (PMID 34308750, 2021). "MALAT1 also promoted tumor invasiveness via regulating the miR-199a/ZHX1 axis." (PMID 34322395, 2021). "Additionally, tumor formation in nude mice also demonstrated that ginkgolic acid inhibits tumor formation in nude mice by downregulating the lncRNA MALAT1/JAK2 axis." (PMID 34987594, 2021). "MALAT1 is found to promote tumor progression by enhancing autophagy." (PMID 34322395, 2021).
tumor (continued). "In vivo experiments showed that the overexpression of MALAT1 promoted the tumor growth of NSCLC." (PMID 34778078, 2021). "previously reported that depletion of MALAT1 inhibits tumor metastasis in mouse GC tissues." (PMID 34001131, 2021). "The lncRNA MALAT1 has been reported to regulate tumor cell metabolism through multiple mechanisms." (PMID 34654454, 2021). "Additionally, IPO7 knockdown reduced the expression of MALAT1 and N-cadherin in the tumor tissues but increased the expression of miR-129-5p and E-cadherin." (PMID 34660566, 2021). "Additionally, we further elucidated correlations between MYST4 and MALAT1 expressions in 26 EOC clinical tumor samples by a real-time PCR, as assessed by Pearson correlations." (PMID 34638541, 2021). "To figure out the mechanism underlying the tumor-suppressive effect of FTO expression on BCa cells, we detected the expressions of the known differentially m6A methylated genes, including MALAT1, CSNK2A2, ITGA6, and NOTCH1, which were found to correlate with BCa progression in previous studies." (PMID 34499008, 2021). "In vivo experiments have shown that MALAT1 gene knockout reduced the tumor growth." (PMID 34778078, 2021). "Consistent with the results observed in vitro, we also found that the OCa tumor weight and volume of nude mice injected with lncRNA MALAT1 overexpression vector were enhanced and JAK2 protein level increased remarkably in comparison to the ginkgolic acid group." (PMID 34987594, 2021). "Furthermore, the result of transwell invasion assay showed a significant reduction of tumor cell invasion in MALAT1 knockdown HepG2 and Bel7402 cells, indicated by significantly less invaded cells when normalized to the control group." (PMID 34001866, 2021). "Notably, the effects of MM tumor progression induced by MALAT1 knockdown were similar with those induced by miR-188-5p upregulation in the present study." (PMID 33944676, 2021). "MALAT1 RNA level correlated with the age, tumor size, and TNM stage." (PMID 34308750, 2021). "Besides the role of MALAT1 in metformin treatment, some other epigenetic regulations would also critical for the anti‐tumour effect of metformin." (PMID 34164906, 2021). "Also, the interaction between PTBP2 and SFPQ regulated by MALAT‐1 RNA is known to promote tumor growth and metastasis." (PMID 34459124, 2021). "Two binding sites of miR-188-5p were found in MALAT1 using online prediction tool, which brought a proper hypothesis that miR-188-5p might mediate the functions of MALAT1 in MM tumor growth." (PMID 33944676, 2021). "MALAT1 was one of earlier investigated long noncoding RNAs in tumor and other fields." (PMID 34308750, 2021). "The RNA level of MALAT1 was significantly related to the tumor purity in eight types of tumors." (PMID 34308750, 2021). "MALAT1 depletion inhibited the tumor volume and weight in contrast with the sh-NC group." (PMID 34222668, 2021). "While MALAT1 was extensively studied and was found to function in multiple cellular processes, including tumorigenesis and tumor progression, the role of mascRNA was largely unknown." (PMID 34001866, 2021). "Metastasis-associated lung adenocarcinoma transcript 1 (MALAT-1), downregulated in CSCs, has been shown to enhance the PCSC fraction, promote self-renewal via Sox2, confer GEM-resistance, accelerate tumor angiogenesis in vitro, and promote PC cell tumorigenicity in vivo." (PMID 34453639, 2021). "Both MALAT1 and miR-188-5p work together to modulate MM tumor development." (PMID 33944676, 2021). "Similarly, MALAT1 sponges the tumor suppressors miR-145 and miR-202-3p, prompting invasiveness and epithelial-mesenchymal transitioning in HeLa cells." (PMID 33450947, 2021). "Furthermore, MALAT1 regulates tumor angiogenesis and progression by activating phosphatidylinositol 3-kinase (PI3K)/Akt, extracellular signal-regulated kinase (ERK)/mitogen-activated protein kinase (MAPK), and Wnt/β-catenin signaling pathways." (PMID 33805687, 2021).
tumor (continued). "In addition, the expression level of MALAT1 is significantly related to the tumor size, stage, metastasis, and distant invasion of NSCLC." (PMID 34778078, 2021). "Moreover, quercetin treatment can significantly decrease tumor volume, weight, and MALAT1 expression in vivo." (PMID 33805687, 2021). "In addition, miR-141-3p inhibitors exhibited to rescue the tumor suppressive effects of sh-MALAT1 on MPM cells." (PMID 34761116, 2021). "From the network diagram, we observe that the sub-network highlights another branch of miR-194-5p, which can directly target the lncRNAs-MALAT1 harboring the rs664589 G allele in the nucleus of CRC cells, thereby regulating the nuclear expression of MALAT1 and exerting a tumor suppressor effect." (PMID 34938735, 2021). "In addition, abnormally elevated MALAT1 expression was also found in LSCC tumor tissues, suggesting a poor prognosis for patients." (PMID 34198263, 2021). "Similarly, PD-L1 and MALAT1 were reported to have antagonistic effect with miR-195, showing the role of miR-195 as tumor suppressor by decreasing expression level of both PD-L1 and MALAT1." (PMID 34679437, 2021). "MALAT1 RNA level also related to tumor size, WHO grade, and Karnofsky Performance Status (KPS)." (PMID 34308750, 2021). "In BC cells, we found that silencing METTL3 could inhibit EMT and tumor cell invasion by suppressing MALAT1." (PMID 34419065, 2021). "Further investigations along these lines could reveal further important information for new insights in MALAT1-induced tumor progression." (PMID 34638541, 2021). "In the present meta-analysis, the pooled results indicated that MALAT-1 expression was not statistically associated with the numbers of tumor, vascular invasion and recurrence, because of the small number of papers." (PMID 33052949, 2020). "Furthermore, MALAT1 overexpression has been related to EMT transition in TPC1 cell lines under the influence of TGF beta action suggesting a role of MALAT1 in tumor metastasis." (PMID 32102500, 2020). "Overall, MALAT1 deletion could strengthen the sensitivity response to Ox via miR-324-3p/ADAM17 axis in xenograft tumor model." (PMID 33005106, 2020). "Although the mechanisms via which MALAT1 exerts both oncogenic and tumor-suppressive functions are not well understood, its functions may depend on context, such as cell type and environment." (PMID 32486413, 2020). "Oncogenic lncRNA MALAT-1 enhances tumor angiogenesis either in CRC or GC." (PMID 32992718, 2020). "It is known that tumor-associated macrophages (TAMs) exhibit similar functions to M2 macrophages and MALAT1 was upregulated in TAMs compared to nonpolarized macrophages and promoted angiogenesis through secretion of fibroblast growth factor-2 (FGF2) protein." (PMID 32190702, 2020). "Furthermore, knockdown of MALAT1 results in a decrease of branching morphogenesis in MMTV-PyMT- and Her2/neu-amplified tumor organoids, increased cell adhesion, and loss of migration." (PMID 32708561, 2020). "In addition, MALAT1 is able to reduce the G2-M phase arrest rate and inhibit apoptosis of irradiated tumor cells by sponging miR-145." (PMID 32122355, 2020). "A study also suggested that MALAT1 plays an important role in tumour progression and could serve as a promising therapeutic target." (PMID 32993558, 2020). "These in vitro and in vivo works demonstrated that high-dose Vc could be a new promising therapeutic agent for the treatment of CRC patients whose tumor was at the high MALAT1 expression level." (PMID 33293956, 2020). "Additionally, MALAT1 knockdown is also seen to completely suppress tumor progression through miR-140-5p elevation and PAK1 inhibition, both in vitro and in TSCC-induced xenograft tumors." (PMID 33123473, 2020). "Therefore, the high expression of MALAT-1 in tumor tissue was related to clinicopathological features of NSCLC with regard to the high heterogeneity observed in tumor size (I2 = 60.5%), LNM (I2 = 83.1%), and TNM stage (I2 = 60.6%)." (PMID 33052949, 2020).
tumor (continued). "As an oncogene, MALAT1 can induce migration and invasion of tumor cells." (PMID 31479414, 2020). "MALAT1 accelerates tumor metastasis, solid tumor formation, and hematologic malignancy development." (PMID 32435156, 2020). "Xenograft tumor assay was implemented to study the influence of MALAT1 on MM in vivo." (PMID 31953613, 2020). "Knockdown of MALAT1 resulted in increased adhesion and decreased migration of tumor cells." (PMID 32771923, 2020). "Moreover, MALAT1 expression has recognized to be an independent prognostic factor in addition to tumor size, FIGO stage, and lymph node metastasis." (PMID 32154165, 2020). "RT‐PCR was applied for detecting the expression of MALAT1 in tumor tissues and para‐cancerous tissues of LSCC patients, which demonstrated that the expression of MALAT1 in LSCC tissues (ie 9.64 ± 0.82) was overtly higher than that in adjacent normal tissues (ie 3.24 ± 1.55) (P < .05)." (PMID 31837057, 2020). "Furthermore, both MALAT1 and SOX9 expressions were associated with age, tumor size, and TNM stage, making these two genes potential candidates for prognosis tools." (PMID 32438606, 2020). "High MALAT1 was significantly correlated with an advanced tumor stage in CRC patients." (PMID 33344634, 2020). "MALAT1 expression was upregulated in HCC tumor samples compared with that in normal tissues." (PMID 32435156, 2020). "Specifically, developing tissue or tumor-specific knockdown of MALAT1 could be considered a valid strategy to restore metabolic control in transformed cells." (PMID 33375130, 2020). "Furthermore, in NSCLC tumor tissues and cell lines (A549 and H1299), MALAT1 can upregulate VIM and downregulate CDH1 and is involved in the phosphorylation of AKT1, RPS6KB1, and MTOR." (PMID 32438606, 2020). "As shown by the results and in tumour/serum samples genotyped as AA, AG and GG, the expression of both MALAT1 and COL5A1 was down‐regulated in a stepwise fashion, while the expression of miR‐145 was increased, suggesting a potential negative relationship between MALAT1/COL5A1 and miR‐145." (PMID 32720739, 2020). "Similarly, ASO-mediated knockdown of MALAT-1 expression resulted in slower tumor growth and metastasis reduction in a mouse mammary carcinoma model." (PMID 32429207, 2020). "Also, the expression of MALAT1 was significantly enhanced in tumor cells after the stimulation with ASCind-EV." (PMID 33015029, 2020). "Besides, in NSCLC tumor tissues and cell lines (A549, H661, and H460), MALAT1 can upregulate CXCL5, which in turn upregulates p-MAPK8 and down-regulates p-MAP2K1/2, p-MAPK3/1 proteins." (PMID 32438606, 2020). "The impacts of MALAT1 on tumor growth in vivo were measured by a xenograft experiment." (PMID 33146951, 2020). "Consistent with this hypothesis, Malat1 KO mice crossed with breast tumor bearing models display a tumor differentiation phenotype." (PMID 32503170, 2020). "Moreover, MALAT-1 exerts a crucial role in tumor progression and metastasis in both TNBC and luminal cells." (PMID 32700729, 2020). "MALAT1 can promote metastasis of COAD via RUNX2 as a survival factor in tumor cells." (PMID 32727450, 2020). "The xenograft tumor model was established to ascertain the impact of MALAT1 on MM in vivo." (PMID 31953613, 2020). "Similarly, the recruitment of miR-30a also reduces the stability of MALAT1 in HNSCC in order to inhibit the invasion capacity of tumor cells." (PMID 33123473, 2020). "In addition, we presented evidence showing that silencing MALAT1 is associated with reduced CD133highCD90high HCC population with suppressed HCC tumorsphere formation and tumor growth in vivo." (PMID 32326045, 2020). "The elevated expression of MALAT1 plays important role in tumor cell progression." (PMID 32209115, 2020). "This transfer of MALAT1 could be one of the possible molecular mechanisms that regulate tumor microenvironment." (PMID 33015029, 2020).
tumor (continued). "MALAT1 level was assayed by qRT-PCR, and the result showed an increased level of MALAT1 in NSCLC significantly associated with lymph node involvement and stage of the tumor." (PMID 33224198, 2020). "Although these results might be limited by the number of samples evaluated, they might also reflect different tumor progression stages in which PCa cells or tissues retain variable degrees of adaptation to MALAT1 depletion." (PMID 33375130, 2020). "Furthermore, in vitro experiments have shown that inhibition of MALAT1 exerts an anti-tumor effect and inhibits cell proliferation and invasion." (PMID 32596158, 2020). "Real‐time PCR and Western Blot analysis were used to study the differentiated expression of miR‐145, MALAT1 (metastasis‐associated lung adenocarcinoma transcript 1) and COL5A1 (collagen alpha‐1(V) chain) in tumour/serum samples genotyped as rs619586 AA, AG and GG." (PMID 32720739, 2020). "Chang and Hu reported that overexpression of MALAT1 could repress the tumor inhibitory effect of miR-125b mimics." (PMID 30988072, 2019). "MALAT1 contains a series of m6A modifications and is upregulated in neoplastic diseases." (PMID 31757221, 2019). "The opposite observation results from disparate studies suggested the complicacy of MALAT1 in BC, which may be according to the specific tumor subtypes or different cell types." (PMID 31214490, 2019). "Furthermore, the overexpression of MALAT1 greatly increased the expression of BIRC5 yet downregulated the expression of miR‐203 in tumour tissues, indicating that MALAT1 sponged miR‐203 for the upregulation of BIRC5 (**P < 0.01)." (PMID 31250518, 2019). "Relative to controls, knocking down MALAT1 in HCC disrupted tumor growth in mice." (PMID 31777593, 2019). "According to recent studies, lncRNA MALAT1 is capable of upregulation of well-established epi-miRNA (subclass of tumor-suppressor miRNA with an ability to revert epigenetic aberrations) called miR-29b characterized by inverse correlation with enhancer of zeste homolog 2 (EZH2) mRNA expression." (PMID 30682861, 2019). "Other types of known tumor-associated lncRNA that are elevated in urinary EVs include the HOXA cluster antisense RNA 2 (HOX-AS-2) and the metastasis-associated lung adenocarcinoma transcript 1 (MALAT-1)." (PMID 30769831, 2019). "Functionally, serum exosome-derived MALAT-1 promoted tumor growth and metastasis." (PMID 31133028, 2019). "The tumor volumes and sizes were greater in the sh‐NC group than in the sh‐MALAT1 group." (PMID 31466138, 2019). "MALAT1 attenuated the tumor suppressive effect of miR-125b mimics by up-regulating STAT3." (PMID 31133028, 2019). "However, high MALAT1 expression was positively correlated with tumor size, MVI, and poor differentiation status." (PMID 31466138, 2019). "Notably, MALAT1 silencing in MM cells through LNA gapmeR antisense olignoculeotides resulted in up-regulation of the tumor suppressor, miR-29b, and significantly inhibits tumor growth both in vitro and in vivo by proteasome blockade." (PMID 31052608, 2019). "In addition, MALAT1 has been reported to regulate tumor cell proliferation through the MAPK pathway." (PMID 30781877, 2019). "Indeed, suz12 (a core component of the polycomb repressive complex 2) knockdown inhibits tumour metastasis in vivo via MALAT1." (PMID 31382922, 2019). "Collectively, we cannot conclude whether MALAT1 is a tumor-promoting or suppressing lncRNA; numerous looping events remain to be discovered to explore the possible explanation for the dual effects of MALAT1 in BC." (PMID 31744046, 2019). "MALAT1 methylation pattern was compared in tumor and polyp tissue." (PMID 32099603, 2019). "For example, in the MMTV-PyMT mouse mammary carcinoma model, MALAT1 could promote tumor growth and metastasis." (PMID 31448238, 2019). "Long noncoding RNAs (LncRNAs), including MALAT1, are critical regulators of tumor development." (PMID 30683916, 2019). "MALAT1 promotes tumor proliferation and metastasis through activation of autophagy." (PMID 30650521, 2019).